BRCA2 (BRCA2 DNA repair associated)
Diseases named in the same sentence as BRCA2 in open-access papers (continued):
Sharing a sentence is not in itself a finding about the gene and the disease.
ovarian carcinoma (continued). "In our previous work, we demonstrated that two variants in BRCA1 (c.2037delinsCC and c.3331_3334del) and one in BRCA2 (c.156_157insAlu) together represent about 50% of all deleterious variants found in Portuguese hereditary breast and ovarian cancer families mostly originated from northern Portugal." (PMID 32850417, 2020). "Thus, it is a unique way for gastrointestinal tumors to develop BRCA2 mutations that is distinct from how these mutations occur in breast and ovarian cancer." (PMID 32980867, 2020). "BRCA2 gene has been proved to carry a high risk of hereditary in breast and ovarian cancer." (PMID 33162799, 2020). "NJ Birkbak and his colleagues provided evidence to suggest that tumor mutation burden analysis could forecast the outcome in ovarian cancer with BRCA1 or BRCA2 mutations." (PMID 33747898, 2020). "Along with 36 cancer-gene associations (FDR < 0.05, Wald test) found in the European ancestry, we identified two specific cancer-gene associations in the African ancestry: BRCA2 in ovarian cancer (OV) (OR = 8.5 [95% CI, 1.5–47.4]; FDR = 0.045) and LUSC (OR = 41.4 [95% CI, 6.1–275.6]; FDR = 0.002)." (PMID 32471518, 2020). "Specific inherited mutations in BRCA2 may notably increase the risk of female breast and ovarian cancers, but they have also been associated with increased risks of several additional types of cancer." (PMID 33643409, 2020). "Hence, BRCA1 and BRCA2 carriers present a risk of 65–80% and 45–85% for developing breast cancer while, for ovarian cancer they present a risk of 37–62% and 11–23% respectively." (PMID 32778078, 2020). "However, increased surveillance and prophylactic surgery (mastectomy and salpingo-oophorectomy) can greatly reduce the risk of breast and ovarian cancer in women carrying a BRCA1 or BRCA2 mutation." (PMID 32376921, 2020). "BRCA1 and BRCA2 are the best-known genes associated with hereditary breast and ovarian cancer." (PMID 32046255, 2020). "Similarly, annotation analysis using the Clinvar database reported that 4 of the associated variants in BRCA2 (rs11571584, rs11571686, rs9567600, rs7337574) are linked with an increased risk of developing breast and ovarian cancer at an earlier age." (PMID 32404140, 2020). "Indeed, high-penetrance germline mutations in DNA repair genes are important players in familial cancers: BRCA1, BRCA2 mutations or mismatch repair, and polymerase deficiency in colorectal, breast, and ovarian cancers." (PMID 32605254, 2020). "Moreover, some authors have noted that BRCA1 and BRCA2 mutations are responsible for the development of almost 90% of all ovarian cancer cases." (PMID 30970628, 2019). "Nonetheless, our current study supports previous studies suggesting that BRCA1 gene and BRCA2 gene mutations may be associated with increased susceptibilities to cancers other than breast and ovarian cancer." (PMID 30622657, 2019). "Heterozygous germline mutations in BRCA2 predispose to breast and ovarian cancer." (PMID 31316060, 2019). "It has been estimated that testing all women diagnosed with HGSC for a BRCA1 or BRCA2 gene mutation could reduce breast and ovarian cancer in first-degree relatives by 20% and 55%, respectively." (PMID 31061661, 2019). "Germline mutations in BRCA1 or BRCA2 gene confer a high risk of developing ovarian cancer." (PMID 31064392, 2019). "BRCA1 and BRCA2 disruption is associated with hereditary breast and ovarian cancers." (PMID 31383866, 2019). "This difference may be the result of a “counselled risk”, based on the lower incidence and the slightly better prognosis of ovarian cancer in BRCA2 mutation carriers." (PMID 30841601, 2019). "A recent study showed that BRCA2-deficient ovarian cancer cells express high levels of POLQ, which may contribute to elevated MMEJ in these cells." (PMID 31109041, 2019). "In addition, we report preferential sensitivity of ovarian cancer cells with BRCA2 mutation to this novel agent." (PMID 31557908, 2019).
ovarian carcinoma (continued). "Pathogenic variants in BRCA1 and BRCA2 cause hereditary breast and ovarian cancer." (PMID 31143303, 2019). "Olaparib, rucaparib, niraparib, and talazoparib targeting PARP1/2 have been approved by the United States Food and Drug Administration (FDA) for the treatment of breast or ovarian cancer in patients harboring HR mutations that induce synthetic lethality in the BRCA1 or BRCA2 gene." (PMID 31795418, 2019). "Women with a BRCA1 or BRCA2 mutation face high risks of breast and ovarian cancer." (PMID 30971774, 2019). "Comparing the BRCA1 (A) and BRCA2 (B) carriers according to personal/family history, it was possible to see that triple negativity, bilateral breast and ovarian cancer in the proband or family were the main factors associated with the presence of a BRCA1 mutation." (PMID 31244284, 2019). "We previously found that SNP rs34259 in the uracil‐DNA glycosylase gene (UNG) might decrease ovarian cancer risk in BRCA2 mutation carriers." (PMID 30747491, 2019). "Moreover, CX-5461 is currently in clinical trial in BRCA mutant breast cancer (Clinical trial identification: NCT02719977) and so we have considered this using an ovarian cancer model with BRCA2 mutation." (PMID 31557908, 2019). "Similarly, mutations in exon 11 of BRCA2 were associated with variability in breast and ovarian cancer risk." (PMID 31379942, 2019). "Family history and the presence of mutations in genes such as BRCA1 and BRCA2 significantly increase the risk of development of ovarian cancer; other factors such as hormonal or reproductive factors can either increase or decrease the likelihood of this disease." (PMID 30820349, 2019). "The SNP rs34259 in the 3′UTR of the UNG gene may decrease ovarian cancer risk in BRCA2 mutation carriers." (PMID 30747491, 2019). "We applied a Mendelian randomisation approach to examine height/BMI with ovarian cancer risk using the Consortium of Investigators for the Modifiers of BRCA1/2 (CIMBA) data set, comprising 14,676 BRCA1 and 7912 BRCA2 mutation carriers, with 2923 ovarian cancer cases." (PMID 31213659, 2019). "Women with a BRCA1 or BRCA2 mutation face elevated risks of breast and ovarian cancer." (PMID 30971774, 2019). "The lifetime ovarian cancer risk for a woman with BRCA1 mutation is estimated to be 35% to 70%, the ovarian cancer risk lifetime for women with BRCA2 mutation is between 10 and 30%; the ovarian cancer lifetime risk for the women in the general population is less than 2%." (PMID 29389895, 2018). "As we all know, mutations in BRCA1 and BRCA2 increase the risk of breast or ovarian cancer." (PMID 30487464, 2018). "In the present study, we describe the development of a multiplexed, SNaPshot primer extension genotyping assay, which allows the rapid and cost-effective detection of targeted BRCA1 and BRCA2 mutations from breast and ovarian cancer patients in Chinese populations." (PMID 29487695, 2018). "Importantly, a more recent study demonstrated that loss of CHD4 leads to therapeutic resistance in BRCA2 mutant ovarian cancer." (PMID 29625565, 2018). "Notably, carriers of pathogenic BRCA1 or BRCA2 variants (path_BRCA1 or path_BRCA2) have an increased risk of developing BC (average lifetime risk of 35–85%) and ovarian cancer (average lifetime risk 11–39%)." (PMID 29371908, 2018). "Specific inherited mutations in BRCA2 increase the risk of female breast and ovarian cancers." (PMID 29805764, 2018). "Also, it seems that the probability of a BRCA mutation (especially BRCA2) increases if there is a significant family history of breast and ovarian cancer." (PMID 29456621, 2018). "The pathogenic variants in BC-related genes (2 in ATM and 1 in BRCA2) were found in 3 women with BC or ovarian cancer, while the MSH6 and the heterozygous MUTYH p.Gly393Asp pathogenic variant was found in a woman with endometrial cancer at 57 years and BC diagnosis at 56 years, respectively." (PMID 29371908, 2018).
ovarian carcinoma (continued). "Since the identification of tumor suppressor genes, BRCA1 and BRCA2, of which germline pathogenic variants predispose to a significant increase in breast and ovarian cancer risk, several other cancer-related genes have been associated with their pathogenesis and progression." (PMID 30441849, 2018). "BRCA2 mutation carriers may be able to delay surgery up to the age of 45 years, as BRCA2 mutation carriers tend to develop ovarian cancer after the age of 50 years." (PMID 30174725, 2018). "Germline or somatic mutations in the BRCA1 or BRCA2 gene have prognostic value in ovarian cancer since ovarian cancer patients with BRCA1/2 mutations are reported to have a better response to platinum-based treatment and subsequently a longer survival duration than patients without such mutations." (PMID 29179445, 2017). "BRCA2 germline mutation predisposes to breast and ovarian cancer." (PMID 28904335, 2017). "Who raises this issue and when it is raised during the consultation depends on many factors, which may include the patient’s pre-test understanding of BRCA1/BRCA2 mutation risks, family history and response to ovarian cancer treatment." (PMID 28780755, 2017). "We hypothesized that common genetic variants in genes involved in BER might modify a woman’s lifetime risk of developing breast and ovarian cancer if she is a BRCA1 or BRCA2 mutation carrier." (PMID 29383107, 2017). "Interestingly, the hazard ratio estimate for the association of the ovarian cancer PRS with ovarian cancer risk was statistically significantly higher for BRCA2 than for BRCA1 mutation carriers." (PMID 28376175, 2017). "FANCM mutation testing in women with HGSOC might also have clinical utility through targeted treatment with Poly (ADP-ribose) polymerase (PARP) inhibitors, which are currently being evaluated in women with BRCA1 and BRCA2 associated ovarian cancer." (PMID 28881617, 2017). "Supporting this hypothesis, previous studies have demonstrated elevated rates of pathogenic mutations in genes other than BRCA1 and BRCA2 (6–7%) among women with ovarian cancer." (PMID 28281021, 2017). "Mutations in BRCA1 and BRCA2 genes are associated with elevated risk of breast and ovarian cancer." (PMID 28729482, 2017). "Heterozygous BRCA1 and BRCA2 mutations increase the risk of breast and ovarian cancers." (PMID 28729482, 2017). "Mutations in BRCA1 and BRCA2 increase the risk of female breast and ovarian cancers." (PMID 28069070, 2017). "Second, individuals who have previously received limited BRCA1 and BRCA2 gene testing may still harbor a genetic risk of breast and/or ovarian cancer and should be considered for multi-gene panel testing including large rearrangement testing." (PMID 28281021, 2017). "In addition, between 5% and 15% of all women with ovarian cancer have inherited mutations in DNA repair genes such asBRCA1,BRCA2, and genes associated with Lynch syndrome." (PMID 28184293, 2017). "Only few of the BRCA2 mutations in CRCs have been reported in breast/ovarian cancer suggesting that these mutations may be CRC-specific." (PMID 28591715, 2017). "Hereditary breast and ovarian cancer is characterized by mutations in BRCA1 or BRCA2 genes and PCR‐based screening techniques, such as capillary sequencing and next‐generation sequencing (NGS), are considered gold standard methods for detection of pathogenic mutations in these genes." (PMID 28717669, 2017). "In addition to BRCA1 and BRCA2, many other proteins are involved in the HR repair process of double-strand DNA breaks and are implicated in hereditary breast and ovarian cancer susceptibility." (PMID 28073364, 2017). "A number of heterozygous mutations in FA-related genes are implicated in the susceptibility to several cancers: BRCA1 and BRCA2 mutations are associated with breast and ovarian cancer and similarly Fanconi anemia complementation group protein J (FANCJ) mutations predispose to breast cancer." (PMID 28471392, 2017).
ovarian carcinoma (continued). "BRCA1 and BRCA2 mutations account for a considerable proportion of Chinese hereditary breast/ovarian cancer patients, and the penetrance of these two genes should be investigated because such investigations will be very important for the development of a preventive treatment strategy in China." (PMID 26852015, 2016). "Larger studies will be required to assess whether the patterns of associations differ by ovarian cancer histological subtyped in BRCA1and BRCA2 mutation carriers." (PMID 27463617, 2016). "Mutations in BRCA1 and BRCA2 genes confer a high risk of both breast and ovarian cancer." (PMID 27876019, 2016). "However, we observed a potentially deleterious BRCA2 germline variant (BRCA2 p.S1946P) in two sisters with ovarian cancer (one with clear cell carcinoma and the other with serous carcinoma)." (PMID 27907908, 2016). "Also, BRCA2 mutation carriers have well documented increased risk of ovarian cancer and the decreased risk of ovarian cancer in geothermal areas in our study further argues against confounding effects of mutation in the BRCA2 gene." (PMID 27205903, 2016). "For example BRCA2 may cause Fanconi aenemia in the homozygous state and familial breast and ovarian cancer in the heterozygous state." (PMID 27809840, 2016). "Patients with BRCA1 mutations were enriched for a family history of breast (5/23 (21.7%)) and ovarian cancers (2/23 (8.7%)), whereas patient cases with BRCA2 mutations were enriched for a family history of breast (7/17 (41.2%)) but none of the family members had ovarian cancers." (PMID 29263802, 2016). "The tumor suppressor genes BRCA1 and BRCA2 are the two major breast and ovarian cancer susceptibility genes, and deleterious mutations in these genes have shown to contribute in the pathogenesis of breast/ovarian cancer." (PMID 27818992, 2016). "Mutations in BRCA2 may result in breast and/or ovarian cancer, pancreatic cancer, and prostate cancer as well." (PMID 27930734, 2016). "BRCA1 and BRCA2 mutations are responsible for hereditary breast and ovarian cancer, but they also confer an increased risk for the development of rarer cancers associated with this syndrome, namely, cancer of the pancreas, male breast, peritoneum, and fallopian tube." (PMID 27532258, 2016). "Germline (g) mutations in either the BRCA1 or BRCA2 genes render individuals at high life-time risk of breast and ovarian cancer and these subsequent cancers may have HRR deficiency (HRD)." (PMID 27002934, 2016). "The mutation status may determine the medical management of patients, including annual screening and prophylactic surgery, and genetic testing for BRCA1 and BRCA2 is routinely performed in women with hereditary breast and ovarian cancer risk." (PMID 25948282, 2015). "Nevertheless, PALB2 mutations and pathogenic mutations in other genes involved in the same pathway as BRCA2 could explain a minor part of the excess of pancreatic and ovarian cancer." (PMID 26082817, 2015). "In our study, some mutations found in BRCA2 (hereditary predisposition for breast and ovarian cancer) or in MLH1 (hereditary predisposition to Lynch syndrome) genes through the genetic characterization of tumors could be germline." (PMID 26155992, 2015). "Mutations in BRCA1 and BRCA2 are associated with susceptibility to breast and ovarian cancer." (PMID 25636233, 2015). "Mutations in the BRCA1 and BRCA2 genes result in predisposition to breast and ovarian cancers." (PMID 26543556, 2015). "Targeted PCR-based genetic testing for BRCA1 and BRCA2 can be performed at a lower cost than full gene testing; however, it may overlook mutations responsible for familial breast and/or ovarian cancers." (PMID 25948282, 2015). "As a significant number of ovarian cancer patients harbour germline BRCA1/BRCA2 mutations, a targeted screen for carriers in this defined population has the potential to improve health management of patients and reduce ovarian cancer risk for their mutation-carrier family members." (PMID 25884701, 2015).
ovarian carcinoma (continued). "Clinical genetic testing of BRCA1 and BRCA2 is commonly performed to identify specific individuals at risk for breast and ovarian cancers who may benefit from prophylactic therapeutic interventions." (PMID 26246475, 2015). "The absence of reliable methods for early detection and the poor prognosis associated with advanced ovarian cancer have supported the recommendation of bilateral risk reduction salpingo-oophorectomy (RRSO) after completion of childbearing in women with BRCA1 or BRCA2 mutation." (PMID 26669313, 2015). "Interestingly, one Fanconi anemia patient has been found to carry a homozygous truncating XRCC2 mutation while biallelic mutations in four breast and ovarian cancer susceptibility genes, BRCA2, BRIP1, PALB2, and RAD51C, are associated with Fanconi anemia." (PMID 25918678, 2015). "Moreover, the 9p22 rs3814113 SNP has been demonstrated to be a protective genetic factor of ovarian cancer for carriers of BRCA1 or BRCA2 mutations." (PMID 25173882, 2015). "The distinction between a BRCA1 and a BRCA2 mutation depended on four factors: ovarian cancers favored BRCA1 mutations (p = 0.00011) while male breast cancers (p = 0.0045), prostatic cancers (p = 0.012) and pancreatic cancer (p = 0.022) were more frequent in BRCA2 mutated families." (PMID 26047126, 2015). "The incidence of germline BRCA2 mutations in apparently sporadic pancreatic cancers may be as high as in breast or ovarian cancer." (PMID 24268522, 2014). "In the Iberian Peninsula, which includes mainly Spain and Portugal, large genomic rearrangements (LGRs) of BRCA1 and BRCA2 have respectively been found in up to 2.33% and 8.4% of families with hereditary breast and/or ovarian cancer (HBOC) that lack point mutations and small indels." (PMID 24686251, 2014). "In addition, an ovarian cancer susceptibility locus 17q11.2 identified through population-based data has been shown to display a consistent association in BRCA2 carriers, whereas an association of similar magnitude has been ruled out in BRCA1 carriers." (PMID 25919761, 2014). "In addition, BRCA1 mutation carriers have a 30-40% chance of developing ovarian cancer, while BRCA2 mutations also increase the risk of ovarian, pancreatic, prostate, and male breast cancer." (PMID 25011685, 2014). "Initial studies soon after the discovery of BRCA2 reported consistent inactivation of the wild‐type BRCA2 allele through loss‐of‐heterozygosity (LOH) in breast or ovarian cancer cells from mutation carriers, engendering the widely accepted view that BRCA2 LOH is an essential event in carcinogenesis." (PMID 24268522, 2014). "Furthermore, there is data indicating that BRCA2 mutation carrying families having one case of ovarian cancer in the family are more likely to develop pancreatic and prostate cancers." (PMID 24959366, 2014). "BRCA1 and BRCA2 are also mutated in patients with ovarian cancer." (PMID 25051360, 2014). "Inherited mutations in BRCA1/BRCA2 for example, increase the risk of breast and ovarian cancer." (PMID 25034939, 2014). "In the present work, 256 unrelated high-risk probands with breast and/or ovarian cancer from families living in Asturias were analyzed for the presence of a BRCA1 or BRCA2 gene mutation from October 2007 to May 2012." (PMID 23683081, 2013). "Until recently, BRCA1 and BRCA2 were the only genes known to confer a considerable risk of ovarian cancer (in conjunction with breast cancer) with two recent studies reporting that 13.3–14.1% of unselected high grade ovarian cancers are accounted for by mutations in one of these two genes." (PMID 23372765, 2013).